GSCAR (glioma stem cell associated long noncoding RNA)
Gene: Long non-coding RNA gene on chromosome 5 (88,691,548 to 88,695,492, reverse strand). Ensembl gene ENSG00000250377.
Diseases named in the same sentence as GSCAR in open-access papers:
GSCAR is named in the same sentence as 3 diseases in open-access papers, as found by Europe PMC text mining. Sharing a sentence is not in itself a finding about the gene and the disease. The quoted sentences say what the papers report.
glioma (1 paper, 2023). A benign or malignant brain and spinal cord tumor that arises from glial cells (astrocytes, oligodendrocytes, ependymal cells). "We revealed that GSCAR was markedly upregulated in glioma cancerous cell lines and preferentially higher in GSCs." (PMID 37063420, 2023). "The high expression of GSCAR in gliomas and its critical role in promoting tumor progression prompted us to exploit the potential of GSCAR as a therapeutic target by using ASO." (PMID 37063420, 2023). "Inhibition or forced expression of GSCAR increased or decreased miR-6760-5p expression, respectively, in glioma tumor cells, which was validated by dual-luciferase reporter assay." (PMID 37063420, 2023). "The positive feedback loop of GSCAR/DHX9-IGF2BP2/SOX2 distinguishes glioma stem cells from other glioma tumor cells regulated by the GSCAR/miR-6760-5p/ SRSF1 axis." (PMID 37063420, 2023). "As expected, the increased expression of GSCAR was confirmed in glioma tissue microarray examined by ISH assay (RNA in situ hybridization)." (PMID 37063420, 2023). "As expected, GSCAR expression positively correlated with glioma stem cell biomarkers, including CD133, CD44, NANOG, ALDH1, Oct4, SOX2, and c-Myc." (PMID 37063420, 2023). "Consistently, we found that GSCAR expression was higher in IDH1 wild-type (WT) gliomas than in IDH1 mutant (MUT) gliomas, and glioma patients with higher GSCAR expression exhibited worse clinical outcomes." (PMID 37063420, 2023). "Furthermore, we found that GSCAR knockdown dramatically inhibited glioma cell migration and invasion abilities." (PMID 37063420, 2023). "Blocking GSCAR expression efficiently inhibits glioma progression, indicating that GSCAR and its related molecular events could be used as novel therapeutic targets for gliomas in the future." (PMID 37063420, 2023). "Based on the fact that GSCs are important for chemotherapy resistance in glioma 7, 41, we decided to verify whether blocking the GSCAR/DHX9-IGF2BP2/SOX2 feedback loop could increase the glioma cell response to TMZ." (PMID 37063420, 2023). "Increased GSCAR expression correlated with poor clinical outcomes in glioma patients." (PMID 37063420, 2023). "In addition, the repressed cell proliferation and migration abilities resulting from miR-6760-5p mimic overexpression can be overcome by GSCAR overexpression, supporting the specific role of the GSCAR/miR-6760-5p axis in gliomas." (PMID 37063420, 2023). "In conclusion, GSCAR might serve as a therapeutic target in gliomas in the future." (PMID 37063420, 2023). "Therefore, one independent ASO specifically targeting GSCAR and the control ASO were designed and transfected into glioma tumor cell lines." (PMID 37063420, 2023). "To investigate the biological function of GSCAR in gliomas, we first performed KEGG analysis to predict the potential molecular events regulated by GSCAR in low-grade gliomas (LGGs), and the cell cycle, Wnt signaling, and focal adhesion-related signaling pathways were identified." (PMID 37063420, 2023). "Our results showed that GSCAR-targeting ASOs alone or in combination with TMZ markedly inhibited glioma tumor cell growth both in vitro and in vivo, suggesting that GSCAR is a promising therapeutic target for glioma patients in the future." (PMID 37063420, 2023). "Therefore, we decided to decipher the potential mechanism by which the GSCAR/miR-6760-5p/SRSF1 axis and GSCAR/DHX9-IGF2BP2/SOX2 feedback loop promote glioma progression, which may provide new therapeutic targets for glioma in the future." (PMID 37063420, 2023). "Interestingly, GSCAR was identified to increase the stemness of glioma stem cells independent of the GSCAR/miR-6760-5p/SRSF1 axis." (PMID 37063420, 2023). "In addition, we confirmed that SRSF1 knockdown inhibited glioma cell growth and migration and showed that SRSF1 overexpression could reverse GSCAR knockdown-reduced cell growth and migration abilities." (PMID 37063420, 2023).
glioma (continued). "Importantly, GSCAR, but not the other 3 lncRNAs, was identified as the only candidate whose functional role in gliomas remains elusive 21-26." (PMID 37063420, 2023). "However, we did not observe that HMGA1 mRNA was significantly reduced after GSCAR knockdown in GSCs, suggesting that HMGA1 could be regulated either by IGF2BP2 or DHX9 in glioma tumor cells in different cellular contexts." (PMID 37063420, 2023).
tumor (1 paper, 2023). "Our results reveal that the GSCAR/miR-6760-5p/SRSF1 axis is important for tumor growth, while the GSCAR/DHX9-IGF2BP2/Sox2 feedback loop is critical for GSC maintenance and TMZ resistance." (PMID 37063420, 2023). "Furthermore, we show that GSCAR knockdown by shRNAs or antisense oligonucleotide (ASO) reduces tumor cell proliferation, migration and xenograft tumor formation abilities." (PMID 37063420, 2023). "We reveal that GSCAR positively correlates with tumor grade." (PMID 37063420, 2023). "In line with previous findings in vitro, GSCAR knockdown markedly inhibited tumor growth in vivo, as evidenced by the decreased Ki67 and increased cleaved caspase 3 (CC3) immunohistochemical (IHC) staining signals, which could be overcome by SRSF1 overexpression." (PMID 37063420, 2023). "We showed that GSCAR interacted with miR-6760-5p to increase the expression of the oncoprotein SRSF1, leading to increased tumor growth and migration in U251 and A172 cells." (PMID 37063420, 2023). "In addition, we showed that GSCAR activates the self-renewal ability of GSCs by mediating DHX9 and IGF2BP2 complex formation, leading to the stabilization of the SOX2 transcript and tumor growth." (PMID 37063420, 2023).
GSCAR also shares sentences with these, for which no sentence is quoted: low grade glioma (1 paper).